RN7SL851P (RNA, 7SL, cytoplasmic 851, pseudogene)
Gene: Miscellaneous RNA gene on chromosome 7 (6,047,721 to 6,048,023, reverse strand). Ensembl gene ENSG00000240718.
Homologues: Orthologues: chimpanzee Metazoa_SRP (99% identical), macaque Metazoa_SRP (91% identical). Paralogues in human: RN7SL1 (81% identical), RN7SL2 (81% identical), RN7SL49P (80% identical), RN7SL650P (80% identical), RN7SL3 (79% identical), RN7SL451P (79% identical), RN7SL296P (79% identical), RN7SL44P (79% identical), RN7SL558P (79% identical), RN7SL15P (78% identical), RN7SL186P (78% identical), RN7SL336P (78% identical), and 705 more.